MEG3 (maternally expressed 3)
Diseases named in the same sentence as MEG3 in open-access papers (continued):
Sharing a sentence is not in itself a finding about the gene and the disease.
breast cancer (continued). "Therefore, it would be expected that expression of MEG3 is higher in normal breast tissue, as it comprises relatively more stromal cells compared to breast cancer tissue." (PMID 32612992, 2020). "We therefore investigated MEG3 expression levels in different subtypes of breast cancer." (PMID 32612992, 2020). "MEG3 expression was reported to be an independent prognostic factor in breast cancer." (PMID 31488093, 2019). "These pathways might be the potential function for MEG3 to affect the response to chemotherapy in breast cancer patients." (PMID 31488093, 2019). "In a pooled analysis, a low expression of MEG3 showed to be associated with low overall survival in cancer patients, but not in the breast cancer patients." (PMID 31488093, 2019). "In summary, we have identified five novel lncRNAs (AL117190.1, COL4A2‐AS1, LINC00184, MEG3 and MIR22HG) related to prognosis of breast cancer, which could act as underlying prognosis biomarkers for breast cancer." (PMID 31613058, 2019). "There have been no analyses published to date of association between MEG3 and chemotherapy response in breast cancer patients." (PMID 31488093, 2019). "To elucidate the clinical role of miR-506 and MEG3 in breast cancer progression, we determined the expression level of these two genes in normal (n = 20) and breast tumor tissues (n = 20), as well as in normal human breast epithelial cells and three breast cancer cell lines." (PMID 30386180, 2018). "There is evidence that lncRNA MEG3 functions as a tumor suppressor in breast cancer metastasis." (PMID 30386180, 2018). "Based on these findings, we hypothesized that MEG3 may be regulated in a DNA methylation-dependent manner in breast cancer cells." (PMID 30386180, 2018). "Previous studies have revealed that overexpression of MEG3 could induce cell growth arrest and increase cell apoptosis in human breast cancer cells." (PMID 30386180, 2018). "However, loss of MEG3 expression has been observed in multiple malignant cancers, including breast cancer, hepatocellular cancer and TSCC, and MEG3 silencing in cancer cells is mainly associated with its promoter hypermethylation." (PMID 29416703, 2018). "In addition, we found that the levels of miR-506 and MEG3 were remarkably decreased (~ 50%) in breast cancer cell lines (MDA-MB-231, MCF-7 and SKBR3) compared to immortalized human breast epithelial cell (MCF10A)." (PMID 30386180, 2018). "In contrast, growth arrest-specific 5 (GAS5) is down regulated in breast cancer and hepatocellular carcinoma, and maternally expressed 3 (MEG3) is downregulation in meningioma and colorectal cancer, indicating that these two lncRNAs are involved in tumor suppression." (PMID 27999202, 2017). "Similar to the trans-actingrole of human MEG3 in breast cancer cells, a recent investigation by Kanekoet al.29 demonstrated that interaction between JARID2 andMEG3 lncRNA is critical for targeting of PRC2 complexes to multiple genesin trans in mouse embryonic stem cells." (PMID 26205790, 2015). "Moreover, higher levels of MEG3 were associated with enhanced overall survival (OS), relapse-free survival (RFS), distant metastasis-free survival (DMFS), and disease-specific survival (DSS) in breast cancer." (PMID 38277283, 2024). "Furthermore, the lncRNA MEG3 was reported as a tumor suppressor in breast cancer." (PMID 36817434, 2023). "Inversely, a decreased expression of the maternally expressed gene 3 (MEG3) lncRNA predicts poor survival in breast cancer (BC) patients." (PMID 36497462, 2022).
breast cancer (continued). "In addition, lncRNA MEG3 has a profound research foundation in tumor diseases, first showing biomarker value in straight-colon cancer, gastric cancer, breast cancer and other cancers." (PMID 36523500, 2022). "Additionally, up-regulating MEG3 inhibited growth of breast cancer." (PMID 35109842, 2022). "In addition, high MEG3 expression restrained growth of breast cancer in vivo." (PMID 35109842, 2022). "Finally, to investigate whether MEG3 influences breast cancer cell growth in vivo, we overexpressed MEG3 in nude mice to observe effect of MEG3 on the tumorigenicity of breast cancer." (PMID 35109842, 2022). "Notably, MEG3 expression was significantly correlated with the prognosis of a total of nine types of cancers, including bladder cancer, brain cancer, breast cancer, head and neck cancer, blood cancer, colorectal cancer, eye cancer, lung cancer, and ovarian cancer." (PMID 34220951, 2021). "In addition, MEG3 inhibits breast cancer growth via upregulating endoplasmic reticulum stress." (PMID 33425489, 2021). "However, there are no investigation to explore the relationship between MEG3 polymorphisms and breast cancer among Chinese women." (PMID 32669097, 2020). "However, there is no data to evaluate the effect of MEG3 polymorphisms on neoadjuvant treatment in the breast cancer." (PMID 31488093, 2019). "However, upstream regulation of MEG3 in breast cancer remain elusive." (PMID 30386180, 2018). "Whether miR-506 cooperates with MEG3 to regulate the metastasis of breast cancer remains unclear." (PMID 30386180, 2018). "Since MEG3 has recently been shown to regulate the TGF-β signaling pathway in breast cancer cells, our data indicate that the combinatorial administration of palbociclib with TGF-β inhibitors (e.g. galunisertib) may be of therapeutic benefit to breast cancer patients." (PMID 27832204, 2016). "Overexpression of MEG3 in breast cancer cell lines MCF7 or MDA-MB-231 prevented cell migration, whereas depletion of MEG3 in human mammary epithelial cell line MCF10A strikingly promoted cell migration." (PMID 40548301, 2025). "We constructed a ceRNA network comprising lncRNA MEG3, miR-330, and CNN1, implying that MEG3 plays a ceRNA role in regulating CNN1 by sponging miR-330 in breast cancer." (PMID 38240701, 2024). "The differential expression of lncRNA MEG3, miRNA-330 and CNN1 was first validated in breast cancer tissues and cells." (PMID 38240701, 2024). "Previous studies have suggested that the long non-coding RNA MEG3 upregulates RBMS3 expression, thereby inhibiting breast cancer proliferation and apoptosis." (PMID 37781074, 2023). "The results revealed that some circulating lncRNAs (MEG3, NBAT1, NKILA, GAS5, EPB41L4A‐AS2, Z38, and BC040587) were significantly down‐regulated in breast cancer patients compared to healthy women." (PMID 36274054, 2023). "MEG3 is downregulated in various cancers and positively correlates with SLFN5 expression in breast cancer." (PMID 37771431, 2023). "UXT is highly expressed in breast cancer and combines with DNMT3B to participate in the methylation regulation of MEG3, thus reducing the expression level of MEG3." (PMID 37901333, 2023). "MEG3 repressed EMT and migration/invasion, similar to our previously reported functions of SLFN5 in breast cancer." (PMID 36033389, 2022). "Through MEG3/miR-4513/phenazine biosynthesis-like domain-containing (PBLD) axis, MEG3 promoted breast cancer cells’ sensitivity to paclitaxel." (PMID 36551518, 2022).
breast cancer (continued). "MEG3, considering as an oncogenic lncRNA, is indicated to affect EMT in various cancer types such as breast cancer, ovarian cancer, lung cancer and gastric cancer." (PMID 36467998, 2022). "DNMT1 and miR-494-3p were highly expressed while MEG3 and OTUD4 were lowly expressed in breast cancer cells." (PMID 35109842, 2022). "Herein, we demonstrated that MEG3 was downregulated in pan-cancers and correlated with SLFN5 expression positively in breast cancer by bioinformatics analysis of TCGA and UCSC Xena data." (PMID 36033389, 2022). "Overexpression of MEG3 inhibits miR-141-3p, activates RNA binding motif single stranded protein 3 (RBMS3), and promotes apoptosis of breast cancer cells." (PMID 36523500, 2022). "We revealed for the first time that MEG3 regulated OTUD4 in breast cancer cells through competitively binding of miR-494-3p, thus regulating growth of breast cancer cells." (PMID 35109842, 2022). "The downregulation of DNMT1 has been reported to suppress progression of breast cancer cells, and DNMT1 also can downregulate maternally expressed gene 3 (MEG3) expression through increasing methylation level of MEG3 in breast cancer." (PMID 35109842, 2022). "Herein, we measured DNMT1, MEG3, miR-494-3p and OTUD4 expression, verified the interaction between them, and then discussed the impact of them on biological function of breast cancer cells." (PMID 35109842, 2022). "MEG3 overexpression of the inactivated PI3K/Akt signaling pathway can inhibit the growth of cervical cancer HeLa cells and breast cancer cells, thus achieving anticancer effects." (PMID 36523500, 2022). "In addition, another limitation of the present study is that we only used a single breast cancer cell line to investigate the potential roles of silencing MEG3 on pyroptosis, it is difficult to confirm whether this effect is universal across other TNBC cell lines." (PMID 34326697, 2021). "We found that in the regulatory network, miR-301a-3p, miR-93-5p, miR-454-3p, miR-181b-5p, XIST, LINC00472, MIR31HG, MEG3, MIR155HG, and LINC00667 have been reported in breast cancer." (PMID 34220926, 2021). "However, deregulation of CARMN, PRINS and MEG3 may be crucial in all subtypes of breast cancer." (PMID 33128008, 2020). "Using analysis of publicly available NGS data using MiPanda we found positive correlation of MEG3 with common EMT markers in normal breast and breast cancer." (PMID 32612992, 2020). "From this analysis, we conclude that AL117190.1, COL4A2‐AS1, LINC00184, MEG3 and MIR22HG act as prognostic biomarkers, whose low expression revealed that patients with breast cancer have better overall survival." (PMID 31613058, 2019). "Recently, emerging evidence has indicated that lncRNAs play pivotal roles in breast cancer tumourigenesis and progression, such as ANCR, ROR, MEG3 and H19." (PMID 31557401, 2019). "Through survival analysis, 5 lncRNAs (AL117190.1, COL4A2‐AS1, LINC00184, MEG3 and MIR22HG) were identified as crucial prognostic factors for patients with breast cancer." (PMID 31613058, 2019). "Maternally expressed 3 (MEG3) gene is a long non-coding RNA that regulates gene expression and has been shown to have tumor suppressive effects in breast cancer, gallbladder cancer, and retinoblastoma." (PMID 31320837, 2019). "MEG3 interacts with the PRC2 complex and suppresses the expression of genes involved in the TGF-β pathway, such as TGFB2, TGFBR1, and SMAD2, in human breast cancer cells, thus inhibiting the SMAD-dependent signaling pathway." (PMID 28598385, 2017). "In addition, MYC has been reported to regulate the expression of several lncRNAs including MEG3 in breast cancer cells, with MYC overexpression enhancing MEG3 level and inhibition of MYC decreasing MEG3 expression." (PMID 40548301, 2025).
breast cancer (continued). "Therefore, we conclude that MEG3 positively modulates SLFN5 expression by sponging miR-146b-5p and inhibits breast cancer development." (PMID 36033389, 2022). "MEG3 has been reported to regulate miR-21, target Caspase-8 to regulate proliferation and apoptosis of psoriatic epidermal cells, and inactivate the PI3K/Akt pathway to promote apoptosis in breast cancer cells." (PMID 36523500, 2022). "In addition, we also studied the methylation status of MEG3 promoter after DNMT1 silencing and the role of MEG3 on breast cancer growth in vivo." (PMID 35109842, 2022). "This is in line with a recent study where high expression of MEG3 was identified to be a negative prognostic marker for breast cancer." (PMID 32612992, 2020). "MEG3 is known to modulate the activity of TGF-β gene expression by forming RNA–DNA triplex structures, thereby binding distal regulatory elements, leading to its transcriptional repression in breast cancer cells." (PMID 30818784, 2019). "In addition to EPB41L4A-AS2, three other lncRNAs, MEG3, WEE2-AS1 and HAND2-AS1, were also applied to examine their potential tumor suppressor roles in breast cancer." (PMID 30764831, 2019). "Regarding breast cancer cell lines, due to limited data availability for the investigated lncRNAs only a partial support was observed, for example MEG3 and Her2-positivity, and MEG3 and grade; otherwise there was a lack of significant data." (PMID 38277283, 2024). "MEG3 could up-regulate OTU deubiquitinase 4 (OTUD4) and RNA binding motif single-stranded interacting protein 3 (RBMS3) by sponging miR-494 and miR-141-3p, respectively, thereby suppressing breast cancer cells proliferation." (PMID 36551518, 2022). "Furthermore, a negative correlation between MEG3 expression and short overall survival, relapse-free survival, and poor prognosis has also been found in breast cancer, NSCLC, and glioblastoma." (PMID 36551518, 2022). "However, the expression of MEG3 was lower in various human tumors compared with that in normal human tissues, including breast cancer." (PMID 32669097, 2020). "Moreover, MEG3 was found to promote cisplatin-induced pyroptosis by promoting the NLRP3/caspase-1/GSDMD axis, implying that MEG3 may be an effective therapeutic target for enhancing breast cancer chemotherapy." (PMID 35392086, 2022). "In addition, MEG3 was found to activate cisplatin-induced cellular pyroptosis by promoting NLRP3/caspase-1/GSDMD axis, implying that MEG3 could be effective therapeutic target of breast cancer." (PMID 34488540, 2021). "Cell experiments showed consistent results that MEG3 (P < 0.01) and CNN1 expression levels (P < 0.05) were markedly decreased in human breast cancer cells MCF-7, BT-474, and MDA-MB-468 compared to those in non-cancerous human breast epithelial cells MCF10A." (PMID 38240701, 2024).
lung carcinoma (78 papers, 2016 to 2025). "In 2016, the role of MEG3 was associated with the epigenetic regulation of the epithelial–mesenchymal transition (EMT) in lung cancer cell line models." (PMID 40149464, 2025). "These experimental data suggest that MEG3 can be used as a diagnostic and therapeutic target for lung cancer by enhancing sensitivity to chemotherapy, acting as a molecular sponge, and other mechanisms." (PMID 36544907, 2022). "Down regulation of lncRNA MEG3 had been reported closely associated with several cancers, such as lung cancer, gastric cancer, etc." (PMID 27634882, 2016). "Additionally, MEG3 genetic polymorphisms were also associated with platinum-based chemotherapy response in lung cancer." (PMID 34199840, 2021). "Interestingly, polymorphisms in lncRNAs of ANRIL (rs1333049) and MEG3 (rs116907618) genes were associated with severe overall and gastrointestinal toxicity in patients with lung cancer treated with platinum-based chemotherapy." (PMID 34525956, 2021). "Besides, MEG3 genotype rs4081134 SNP (AA) was associated with a lung cancer risk in Chinese patients." (PMID 32438606, 2020). "In addition, expression of phosphorylation-deficient mutant of pRb increased MEG3 levels in both lung cancer cell types." (PMID 27832204, 2016). "further confirmed that lncRNA MEG3 is expressed at low levels in NSCLC and that MEG3 can act as a ceRNA to bind miR-543 and affect autophagy in lung cancer cells by regulating the IDO pathway." (PMID 40746614, 2025). "The ARlncRNA MEG3 has been observed to enhance sensitivity to vincristine by impeding autophagy in the context of lung cancer chemotherapy." (PMID 37588204, 2024). "In lung cancer tissues that are resistant to chemotherapy, the lncRNA MEG3 is markedly downregulated." (PMID 39170516, 2024). "The internalization of CAF-origin EVs by lung cancer cells results in elevated MEG3 and SNHG12 levels, conferring cisplatin resistance." (PMID 39717771, 2024). "So, MEG3 as a ceRNA plays an important role in the stem cell-like state of lung cancer cells and inhibits migration and invasion in NSCLC via the miR-650/SLC34A2 axis." (PMID 39170516, 2024). "It has been demonstrated that HNRNPA2B1-mediated m6A modification of lncRNA MEG3 facilitates tumorigenesis and metastasis of nonsmall cell lung cancer cells by regulating the miR-21-5p/PTEN axis." (PMID 39268079, 2024). "The overexpression of MEG3 also enhanced cisplatin sensitivity in cisplatin-resistant lung cancer cells by regulating the miR-21-5p/SOX7 axis, in vitro and in vivo models, impeding cell proliferation, and inducing apoptosis." (PMID 36778005, 2023). "The results from an analysis of the TCGA database revealed that reduced MEG3 gene expression in human lung cancers disrupted the Rb pathway." (PMID 36851033, 2023). "Recognized as a prominent regulator, the lncRNA MEG3 has been documented to function as a vital regulatory element in the context of lung cancer." (PMID 37705098, 2023). "MEG3 is a lncRNA that is abundantly expressed in most normal tissues but downregulated in a variety of tumor tissues including lung cancer." (PMID 36726728, 2023). "In lung cancer cell lines A549 and H292, increasing MEG3 expression can reduce the viability and growth of lung cancer cells and enhance the tumour‐inhibiting effects of VCR." (PMID 37837401, 2023). "In light of the two studies mentioned that both outline MEG3 as a tumour suppressor molecule, more preclinical studies are required to solidify the use of MEG3 as a useful predictor of reduced metastasis in both lung cancer and NB." (PMID 36983973, 2023). "Recently, several studies have shown that MEG3 expression level is reduced in lung cancer, hepatocellular carcinoma, and gastric cancer (46, –, 48)." (PMID 37074188, 2023). "As evidence, MEG3 overexpression has been shown to promote sensitivity to vincristine in lung cancer by inhibiting autophagy markers such as LC3-II." (PMID 36983973, 2023).